STAT3 (signal transducer and activator of transcription 3)
Diseases named in the same sentence as STAT3 in open-access papers (continued):
Sharing a sentence is not in itself a finding about the gene and the disease.
cancer (continued). "STAT3 activation contributes to the expression of antiapoptosis proteins, such as Bcl-xL and Mcl-1, thus decreasing natural apoptotic cell death and favouring cancer cell growth." (PMID 37298475, 2023). "As an oncogene, STAT3 contributes to numerous cellular processes, including cell proliferation, differentiation, angiogenesis, survival, invasion, metastasis, immune response, and suppression of apoptosis in cancer cells." (PMID 38017510, 2023). "Therefore, RUNX1 and STAT3 inhibitors are also expected to have therapeutic value in the treatment of mTORC1-related cancers." (PMID 37760803, 2023). "Thus, the targeting NFκB/STAT3-dependent TWIST activation offers a great promise as one of the possible targets in cancer pharmacotherapy." (PMID 37460910, 2023). "As an oncogene, STAT3 alteration may lead to cancer initiation and progression; therefore, we analyzed STAT3 alterations in different cancers using the cBioPortal database." (PMID 36977736, 2023). "Additionally, EGFR-mediated Signal Transduction and Transcription Factor 3 (STAT3) signaling activation promote cell proliferation and glycolysis in various cancers." (PMID 37944197, 2023). "Therefore, a deeper understanding of the IL-6/STAT3 signaling pathway is needed to promote the overall survival of patients with cancer." (PMID 36720310, 2023). "STAT3 is a key regulator of cancer cell proliferation and survival." (PMID 37759808, 2023). "Secondly, CD24 may enhance the proliferation and survival of cancer cells through the Src/STAT3 pathway." (PMID 38137380, 2023). "Silencing of miR-218-5p inhibited activation of the JAK2/STAT3 pathway by targeting KLF9, while KLF4, which belongs to the same family, could inhibit the JAK2/STAT3 pathway, which in turn affects cancer cell development." (PMID 37465460, 2023). "Moreover, elucidating the articulated network of NRF2, influenced by many unilateral and reciprocal interactions, recapitulated in the “NRF2-ome” or that of STAT3 will likely open new avenues in the prevention or treatment of cancer." (PMID 37000324, 2023). "Signal transducer and activator of transcription 3 (STAT3) is a key transcription factor that regulates gene expression related to inflammation, cell transformation, survival, proliferation, invasion, angiogenesis, and metastasis in cancer." (PMID 37238935, 2023). "STAT3 promotes the expression of hTERT in human cancer and primary cells." (PMID 37612721, 2023). "The role of STAT3 in cancer metastasis, including in OvCa, has been extensively characterized." (PMID 37173951, 2023). "Therefore, the JAK/STAT3 signaling pathway was considered as an effective therapeutic target for numerous cancers." (PMID 37103357, 2023). "This may be explained by the fact that HGSOC is a heterogeneous cancer, with constitutive activation of multiple signalling pathways including STAT3 and NFκB, which may explain its aggressive nature and early invasiveness." (PMID 36765633, 2023). "In addition, NF-κB/IL-6/STAT3 axis plays a key role in cancer chemotherapeutic resistance, where NF-κB can activate IL-6, which then can subsequently activate STAT3 through its receptor." (PMID 37818040, 2023). "As STAT3 is also an essential transcription factor for many normal physiological processes, this unique feature may empower CADs to inhibit STAT3 in a more cancer-specific manner." (PMID 36807142, 2023). "In addition to STAT3-mediated PD-L1 upregulation in cancer cells, activated STAT3 also upregulates the expression of immune checkpoint molecules on the cell surface of immune cells, including regulatory T-cells, B-cells, CD4, CD8, and MDSCs." (PMID 36672335, 2023). "Interestingly, EGFR activation is a known regulator of the transcription factor STAT3, which itself is a key player in a myriad of cancers including RCCs." (PMID 37355607, 2023).
cancer (continued). "Blocking the gp130/STAT3 signaling pathway may eliminate CSCs and help prevent cancer, due to the important role that this pathway plays in maintaining CSC properties such as self-renewal abilities in carcinogenesis." (PMID 35565185, 2022). "STAT3 is overexpressed in approximately 70% of cancers and is a potential cytoplasmic protein." (PMID 36313702, 2022). "Furthermore, there is constitutive activation of STAT3 signaling in cancer that inhibits both apoptosis and antitumor immunity." (PMID 35511379, 2022). "During HP infection, the expression of IL6 in the gastric mucosa was upregulated, and IL6 can promote the activation of signal transducer and activator of transcription 3 (STAT3), which is closely related to the occurrence, development, and metastasis of malignant tumors." (PMID 35958524, 2022). "Notable monogenic PIDs, whose genetic background directly predisposes to cancer, include the activated phosphoinositide 3-kinase δ syndrome (APDS), nuclear factor kappa B subunit 1 (NF-κB1) insufficiency, and Signal transducer and activator of transcription 3 (STAT3) gain-of-function syndrome." (PMID 35250968, 2022). "Moreover, we observed changes in the abundance of ELAVL1 and STAT3, which are activated in skeletal muscle and promote skeletal muscle atrophy in cancer." (PMID 35563153, 2022). "Combining these results and the findings suggesting direct interaction of PVT1 and CypB, we were interested in whether the connection between PVT1 and CypB play roles in STAT3 function in cancer cells." (PMID 36266267, 2022). "Recently, roles of NF-κB and STAT3 in many cancers have been extensively studied." (PMID 36188592, 2022). "A significant link between inflammation and cancer has been confirmed for NF-κB and STAT3." (PMID 36613784, 2022). "Extensive evidence shows that STAT3 overactivation induces angiogenesis, immunosuppression, and metastasis, and suppresses apoptosis and inflammation, eventually resulting in PC among other cancers." (PMID 35288541, 2022). "Here we report that n-3 PUFAs may be an ideal cancer chemo-preventive candidate by targeting STAT3 signaling, which is involved in cell proliferation and apoptosis." (PMID 35566382, 2022). "Consistently, IL-6/STAT3 signaling in cancerous EMT also results in the acquisition of cancer stemness in cancer cells; the self-renewal and population expansion of CSCs requires STAT3 in cooperation with stem-cell-associated transcription factors, such as NANOG." (PMID 36010693, 2022). "Thus, STAT3 transcriptional activity in cancer cells occurs at the level of IL-6-induced nanodroplets, which comprise phase-separated biomolecular condensates." (PMID 35406728, 2022). "SENP3 is a cancer-promoting protein, which up-regulates protein level of STAT3." (PMID 36227136, 2022). "Although STAT3 reportedly plays a role in autophagy of some cells, its role in cancer cell autophagy remains unclear." (PMID 35670018, 2022). "STAT3 is also tightly related to VEGF in cancer progression." (PMID 35123491, 2022). "DDIAS is also involved in homologous recombination DNA repair and IL-6/STAT3 signaling activation, which may contribute to cancer progression." (PMID 35681031, 2022). "Thus, our findings suggest the PIKE-A/STAT3/FTO/SDHA axis as promising anti-cancer treatment targets." (PMID 36232604, 2022). "Increased production of pro-inflammatory molecules such as cytokines, ROS, COX-2, and transcription factors such as NF-B, AKT, activator protein 1 (AP1), and signal transducer and activator of transcription 3 (STAT3) is induced by inflammation, leading to the initiation and progression of cancer." (PMID 35774546, 2022). "In addition, cancer-associated fibroblasts with EMT-program were enriched in HG_M, participating in angiogenesis and immune regulation, such as IL6/STAT3 pathway activity." (PMID 35935940, 2022). "Therefore, numerous studies support STAT3 as a promising therapeutic target for human cancer treatment, especially in GC." (PMID 36443287, 2022).
cancer (continued). "Our data indicating activated STAT3 may support the induction of Il-6 mRNA via contributing to stabilisation of NF-κB in the nucleus, leading to chronic activation of NF-κB as shown in cancer models." (PMID 36275769, 2022). "Persistent activation of STAT3 is poor prognostic indicator in some cancers." (PMID 36700235, 2022). "STAT3 expression positively correlated with the infiltration of resting memory CD4+ T and naive B cells in most tumors and negatively associated with the infiltration of TFHs, CD8+ T, activated NK, and memory B cells in different cancer types." (PMID 36176415, 2022). "To determine whether STAT3 MC exhibits antiproliferative activity in various human cancer cell lines, we next treated seven different cancer cell lines, including MDA-MB-231 cells, with mc-2Stat3 at a fixed concentration of 10 nM." (PMID 35847174, 2022). "Overall, we discovered 64 STAT3 somatic mutations in the 193 donors, of which 63 were non-synonymous and 77% have been previously reported in cancer or lymphoproliferative disease." (PMID 36441748, 2022). "STAT3 was proven to be a cancer-promoting factor and a valuable prognostic marker in UTUC." (PMID 36230984, 2022). "In addition, transcription factor STAT3, as the target protein drug resistance, is also associated with the sensitivity of DDP in cancer." (PMID 35668940, 2022). "Several cancer-related pathways may be more active in high-risk LGGs, such as IL6 JAK STAT3 signaling pathway." (PMID 36193491, 2022). "These negative regulators either block the STAT3 signaling pathway or directly act on the STAT3 protein and, thus, may inspire new ideas for cancer treatment." (PMID 35356799, 2022). "NB is introduced as a small molecule inhibitor of signal transducer and transcription factor 3 (STAT3), a key regulator of stemness, which activities has been shown to induce apoptosis and impair self-renewal in cancer stem cells (CSCs) of several types of cancers." (PMID 36180880, 2022). "Targeting STAT3 activation will be important in cancer immunotherapy." (PMID 35927628, 2022). "Signal transducer and activator of transcription 3 (Stat3) is responsible for many aspects of normal development and contributes to the development and progression of cancer through regulating epithelial cell identity and cancer stem cells." (PMID 36017196, 2022). "Moreover, an SPHK1-driven NF-κB/IL-6/STAT3/S1PR1 amplification loop, was also essential for the development and progression of colitis-associated cancer." (PMID 36361531, 2022). "STAT3 is an oncogenic transcription factor that enhances cancer cell growth and invasion." (PMID 36313702, 2022). "STAT3 pathway is aberrantly activated in cancer and is a potential target for cancer therapy." (PMID 36320056, 2022). "Furthermore, WT cancer stroma had a higher level of phospho‐Stat3, Vegfa, Vegfb and Vegfc than those in Pdia4–/– stroma (2nd to 5th rows)." (PMID 35170261, 2022). "Janus kinase 2 (JAK2) is a tyrosine kinase that activates the signal transducer and activator of transcription 3 (STAT3) transcription factor, which has been involved in the progression of most types of cancers including GB, which is required for GSC growth and self-renewal." (PMID 35562901, 2022). "In malignant tumors, sustained growth signals result in a state of continuous STAT3 activation." (PMID 36104717, 2022). "It is suggested that STAT3/Nrf2 can be an effective target for cancer prevention or treatment." (PMID 36014573, 2022). "Conversely, STAT3 can function as an upstream mediator of autophagy in cancer." (PMID 35317831, 2022). "This study reveals a previously unknown regulatory node of the STAT3 pathway that may be important for the development of novel strategies to treat STAT3-driven cancers." (PMID 34953855, 2022). "Several cancer-related pathways may be more active in high-risk LGGs, such as IL6 JAK STAT3 signaling pathway and ECM receptor interaction." (PMID 36193491, 2022).
cancer (continued). "Moreover, STAT3 can modify NFkB post-translationally by acetylation affecting the prolongation of nuclear retention and the activity of NFkB, which play roles in cancer development." (PMID 35269689, 2022). "Thus, the therapeutic endeavor to target STAT3 is meritorious for treating cancers, and various strategies have been postulated in this regard." (PMID 36080130, 2022). "For example, the expression of STAT3 is dysregulated in various cancers." (PMID 36340269, 2022). "Furthermore, EGCG inhibits signal transducer and activator of transcription 3 (STAT3), which is an oncogene that supports cell survival, proliferation, motility, and progression of the cancer cells." (PMID 35956766, 2022). "High levels of activated STAT3 have been observed in several types of cancer, including human BC." (PMID 36299882, 2022). "Inhibition of oncogenic transcription factors is the object of two ongoing trials, aimed at testing the siRNA-mediated inhibition of c-Myc in multiple solid tumors or hepatocellular carcinoma, and seven clinical trials dealing with Stat3-targeted ASOs in advanced cancers." (PMID 35326630, 2022). "IL-6 is an activator of Stat3 and is elevated in a variety of cancers." (PMID 36080130, 2022). "Besides, the activation of STAT3 by glutamine in OVCA has been already unraveled, and it has been reported that Gln deprivation regulates STAT3 phosphorylation, thereby causing the cancer metabolic switch." (PMID 36077501, 2022). "Multiple biologicalGO enrichments in the candidates could be dissected, for example,response to leptin and regulation of proteolysis increased in cancer(including STAT3 and transgelin (TAGL))." (PMID 35605973, 2022). "Besides, recent studies have also confirmed that STAT3 can participate in the cancer process by mediating the expression of Sox4." (PMID 35513871, 2022). "Transcriptomic studies focusing on STAT3/IL-6 signaling at various stages of gastric disease and cancer could improve mechanistic understanding of this pathway’s role in carcinogenesis." (PMID 35757757, 2022). "Thus, the two compounds are promising lead compounds for the treatment of cancers with hyper-activated STAT3." (PMID 35712699, 2022). "Furthermore, active STAT3 binds to human cyclin D1 promoters and raises cyclin D1, which is connected to cancer progression and development." (PMID 35566382, 2022). "Furthermore, primary macrophages secrete IL-6, which in turn increase IL-6 secretion from cancer cells, where IL-6 is shown to perpetuate this vicious cycle by generating more aggressive M2 macrophage polarization by activating Stat3 phosphorylation." (PMID 35960749, 2022). "STAT3 is a transcription factor that promotes cancer growth and muscular cachexia." (PMID 35565236, 2022). "Although M1-like TAMs show generally anti-tumoral effects, they may induce chronic inflammation, whereas the TIMP-1/IL-6 loop might foster STAT3 activation in cancer cells." (PMID 36291767, 2022). "In addition, functional assays were conducted to determine the effect of APE1 shRNA on malignant phenotypes of cancer cells in vitro and in vivo and the activation of IL‐6/STAT3 signalling." (PMID 35605028, 2022). "Also EGCG treatment for cancers such as breast cancer, has been shown that inhibit the activity of STAT3." (PMID 36581900, 2022). "Among them, IL-6/janus kinase 2 (JAK2)/signal transducer and activator of transcription 3 (STAT3) signaling pathways may play a key role in the development of malignant tumors, participating in the entire process of invasion and metastasis." (PMID 36591515, 2022).
cancer (continued). "However, cancer cells exhibit constitutively activated STAT3, which is attributable to upregulated tyrosine kinases and the deregulation of its negative regulation by suppressors of cytokine signaling proteins." (PMID 35327992, 2022). "Thus, STAT3 dimers translocate in the nucleus to enhance the signaling through transcription factors such as c-jun, erg-1, and c-myc, which are involved in cancer cell proliferation." (PMID 36291602, 2022). "p-Ser727 STAT3 also controls mitochondrial respiration and Ras transformation in cancer cell lines." (PMID 35928250, 2022). "Moreover, there is a significant correlation between downstream proteins regulated by STAT3 and lymph node metastasis, cancer stages, recurrence, and death in patients with lingual squamous cell carcinoma." (PMID 35356799, 2022). "On the other hand, the IL-6/STAT3 pathway increases miR-92a and miR-18a expression by directly targeting its promoter, which resulted in the activation of the Wnt/β-catenin signaling pathway and the promotion of the stem-like phenotype of cancer cells." (PMID 36499093, 2022). "Future work will be conducted to investigate whether reduction in lncARSR or STAT3 levels might inhibit other cancer progression by boosting the immune response." (PMID 35637970, 2022). "EriB is a promising candidate in cancer therapy capable of reducing proliferation and cell viability as well as inducing cell cycle arrest and apoptosis via targeting molecular pathways such as STAT3." (PMID 35317831, 2022). "Furthermore, recent data indicate that cancer cells dynamically exploit Stat3 activity, whereby both Stat3 activation and inactivation support cancer progression in a time- and space-dependent manner." (PMID 36017196, 2022). "STAT3 increases the expression of many genes related to cancer." (PMID 35799305, 2022). "Thus, intense efforts have been made to identify suitable anti-STAT3 agents to treat human cancers such as HCC." (PMID 35566382, 2022). "Likewise, natural products (e.g., resveratrol, flavopiridol, indirubin, magnolol, piceatannol, parthenolide, EGCG, cucurbitacin Q, and curcumin) have been demonstrated to downregulate the activity of STAT3 in cancer cells." (PMID 35401182, 2022). "Dysregulation of STAT3 contributes to a variety of human cancers as well as many human illnesses." (PMID 36142231, 2022). "Cancer-derived exosomes can promote macrophage polarization into M2 macrophages and the expression of PD-L1 in these macrophages by upregulating phosphorylated STAT3 and further enhancing the immunosuppressive effect." (PMID 35279217, 2022). "The STAT3 signaling hub is overactive in many cancers, including the four under discussion here." (PMID 35626167, 2022). "Furthermore, we demonstrate that SLC-0111 is able to potentiate Cis-Pt effect on altered signaling pathways involved in cancer progression such as STAT-3, AKT and ERK decreasing the expression levels of the phosphorylated/activated forms of these proteins." (PMID 35365193, 2022). "Among them, several genes that promote tumorigenesis in cancer cells, including STAT3, HES1, and genes related to NF-κB signaling could be targeted by miR-23a and miR-146b." (PMID 34316033, 2022). "Thus, it is clear that the dysregulation of STAT3 in innate immune cells augments cancer cell proliferation and inhibits antitumor responses via the immunosurveillance system." (PMID 36010693, 2022). "Indeed, pre-clinical studies have demonstrated that STAT3 is activated in muscle mediated by IL-6 excess and significantly contributes to muscle wasting during cancer." (PMID 35847939, 2022). "NF-κB and STAT3 are important transcription factors linking inflammation to cancer." (PMID 35890318, 2022). "By binding to the promoters of Oct4, Nanog, and Sox2, STAT3 could regulate the gene expression of some cancer stem-like cell markers, which may contribute to carcinogenesis and progression." (PMID 35087591, 2022).